PLA2G4A (phospholipase A2 group IVA)
Description:
Has primarily calcium-dependent phospholipase and lysophospholipase activities, with a major role in membrane lipid remodeling and biosynthesis of lipid mediators of the inflammatory response. Plays an important role in embryo implantation and parturition through its ability to trigger prostanoid production (By similarity). Preferentially hydrolyzes the ester bond of the fatty acyl group attached at sn-2 position of phospholipids (phospholipase A2 activity). Selectively hydrolyzes sn-2 arachidonoyl group from membrane phospholipids, providing the precursor for eicosanoid biosynthesis via the cyclooxygenase pathway. In an alternative pathway of eicosanoid biosynthesis, hydrolyzes sn-2 fatty acyl chain of eicosanoid lysophopholipids to release free bioactive eicosanoids. Hydrolyzes the ester bond of the fatty acyl group attached at sn-1 position of phospholipids (phospholipase A1 activity) only if an ether linkage rather than an ester linkage is present at the sn-2 position. This hydrolysis is not stereospecific. Has calcium-independent phospholipase A2 and lysophospholipase activities in the presence of phosphoinositides. Has O-acyltransferase activity. Catalyzes the transfer of fatty acyl chains from phospholipids to a primary hydroxyl group of glycerol (sn-1 or sn-3), potentially contributing to monoacylglycerol synthesis.
Synonyms: cPLA2; PLA2G4; cPLA2-alpha; GURDP
Tractability: Small molecule: a drug acting on it is in phase 2 or 3 trials; a high-quality ligand is known; it has a binding pocket of medium quality; it belongs to a druggable protein family. PROTAC: UniProt records ubiquitination sites on it; ubiquitination databases record sites on it; its protein half-life has been measured; a small molecule that binds it is known.
Target class: Enzyme
Safety:
Unwanted effects reported when the protein is acted on. In parentheses: how it was acted on, where the effect was seen, and who reports it.
hypercholesteremia (source: ClinPGx)
urticaria (source: ClinPGx)
Gene: Protein-coding gene on chromosome 1 (186,828,949 to 186,988,986, forward strand). Ensembl gene ENSG00000116711.
Subcellular location: Cytoplasm; Golgi apparatus membrane; Nucleus envelope
Subcellular location (Human Protein Atlas): Cytosol; Vesicles
Pathways (Reactome):
Metabolism: Acyl chain remodeling of CL; Acyl chain remodelling of PC; Acyl chain remodelling of PE; Acyl chain remodelling of PG; Acyl chain remodelling of PI; Acyl chain remodelling of PS; Arachidonate metabolism; Hydrolysis of LPC; Synthesis of PA
Hemostasis: ADP signalling through P2Y purinoceptor 1; Platelet sensitization by LDL
Signal Transduction: phospho-PLA2 pathway
Vesicle-mediated transport: COPI-independent Golgi-to-ER retrograde traffic
Gene Ontology:
Molecular function: acyltransferase activity, transferring groups other than amino-acyl groups; calcium ion binding; calcium-dependent phospholipid binding; ceramide 1-phosphate binding; phosphatidylcholine lysophospholipase activity; phosphatidylinositol-3-phosphate binding; phosphatidylinositol-4-phosphate binding; phosphatidylinositol-5-phosphate binding; phospholipase A2 activity; phospholipase activity
Biological process: arachidonate metabolic process; leukotriene biosynthetic process; monoacylglycerol biosynthetic process; phosphatidylcholine acyl-chain remodeling; phosphatidylcholine catabolic process; phosphatidylglycerol catabolic process; positive regulation of platelet activation; prostaglandin biosynthetic process; glycerophospholipid catabolic process; icosanoid metabolic process; platelet activating factor biosynthetic process; arachidonate secretion; glycerophospholipid metabolic process; phospholipid catabolic process; positive regulation of macrophage activation; positive regulation of T-helper 1 type immune response
Cellular component: cytoplasm; cytosol; Golgi membrane; nuclear envelope; endoplasmic reticulum; endoplasmic reticulum membrane; Golgi apparatus; mitochondrial inner membrane; nucleus
Genetic constraint (gnomAD): Loss-of-function variants: 6 observed, 13.31 expected, observed/expected ratio (o/e) 0.45, 90% interval 0.25 to 0.89. The upper end of that interval is the gene's LOEUF score, 0.89, which puts it in group 3 of 6, group 1 being the genes least tolerant of losing a copy. Missense variants: 180 observed, 249.98 expected, observed/expected ratio (o/e) 0.72, 90% interval 0.64 to 0.81. Synonymous variants: 85 observed, 83.34 expected, observed/expected ratio (o/e) 1.02, 90% interval 0.86 to 1.22.
Gene-disease validity (ClinGen):
ClinGen rates the evidence that PLA2G4A causes each of these diseases.
cytosolic phospholipase-A2 alpha deficiency associated bleeding disorder (autosomal recessive): Moderate.
Homologues: Orthologues: chimpanzee PLA2G4A (99% identical), macaque PLA2G4A (99% identical), rat Pla2g4a (95% identical), mouse Pla2g4a (94% identical), rabbit PLA2G4A (94% identical), guinea pig PLA2G4A (94% identical), pig PLA2G4A (91% identical), tropical clawed frog pla2g4a (81% identical), zebrafish pla2g4aa (71% identical), zebrafish pla2g4ab (68% identical). Paralogues in human: PLA2G4F (30% identical), PLA2G4E (30% identical), PLA2G4D (27% identical), PLA2G4B (26% identical), PLA2G4C (17% identical).
Diseases named in the same sentence as PLA2G4A in open-access papers:
PLA2G4A is named in the same sentence as 117 diseases in open-access papers, as found by Europe PMC text mining. Sharing a sentence is not in itself a finding about the gene and the disease. The quoted sentences say what the papers report.
breast carcinoma (9 papers, 2013 to 2024). "Finally, we explored the association of CD4+ and CD8+ T cells with cPLA2 (PLA2G4A) gene expression in invasive basal-like breast cancer patients using the TIMER database." (PMID 35135586, 2022). "Inhibiting lipid metabolism in effector T cells through reprogramming with group IVA phospholipase A2 (PLA2G4A) has a favorable effect on preventing ex vivo T cell senescence, which has been validated in mouse models of melanoma and breast cancer." (PMID 39684260, 2024). "We further tested the correlation between S100A7 and PLA2G4A gene expression in breast cancer patients using the SEEK database (Search-Based Exploration of Expression Compendium)." (PMID 35135586, 2022). "Firstly, we analyzed the clinical significance of S100A7 and cPLA2 (PLA2G4A) in invasive breast cancer using publically available breast cancer datasets and human breast cancer tissue microarray (TMAs) by immunohistochemistry analysis." (PMID 35135586, 2022). "We discovered that S100A7 showed a significant positive correlation with PLA2G4A in breast cancer patients, mainly in breast invasive carcinoma." (PMID 35135586, 2022). "Higher expression of PLA2G4A is positively correlated with the migration and invasion of lung cancer cells and unfavorable prognosis in breast cancers." (PMID 36046688, 2022). "Furthermore, we analyzed the correlation of S100A7 and PLA2G4A using the cBioPortal for cancer genomics database, which contains a large number of breast cancer samples of different subtypes." (PMID 35135586, 2022). "We also evaluated the prognostic significance of S100A7 and PLA2G4A alone or in combination and overall survival (OS) probability of immunomodulatory (IM) subtype of breast cancer patients using the Kaplan Meier (KM)-plotter [Breast cancer] tool (gene chip)." (PMID 35135586, 2022). "We observed that only the basal subtype of breast cancer showed significantly high levels of S100A7 (p-value = 1.81e-22) and PLA2G4A (p-value = 1.45e-54) as compared to normal subjects." (PMID 35135586, 2022). "A study comparing MDA-MD-231 breast cancer cells observed a significant decrease in PLA2G4A - a PLA2 isoform that was not significantly detectable in our cells." (PMID 23626839, 2013).
colorectal cancer (7 papers, 2021 to 2025). A primary or metastatic malignant neoplasm that affects the colon or rectum. "Furthermore, PLA2G2A and PLA2G4A have been implicated in the pathogenesis of various cancers, such as gastric cancer, colorectal cancer, and prostrate cancer." (PMID 37095470, 2023). "PLA2G4A activates the colorectal cancer microenvironment to produce pro-cytokines IL-17A and adenosine, thereby establishing an effective immunosuppressive microenvironment and promoting immune evasion and tumor metastasis." (PMID 36120336, 2022). "Studies have shown that the PLA2G4A gene can be used as a biomarker in various diseases such as gastric cancer, acute myeloid leukemia, cholangiocarcinoma, and colorectal cancer." (PMID 36120336, 2022).
gastric cancer (6 papers, 2009 to 2024). A primary or metastatic malignant neoplasm involving the stomach. "Reduced expression of Pla2g4a is common in gastric cancer and is significantly associated with tumor size and grade." (PMID 33396408, 2020). "In PLA2G4A, a mutation was detected in the UPF1 siRNA-transfected GP202 gastric cancer cells, at position 1012 (mRNA seq NM_024420.1) resulting in a C to T substitution at position 303 of the protein, but this mutation did not result in a different amino acid (GAC to GAT (Aspartate))." (PMID 19563644, 2009). "The genes PLA2G4A, BMP5, MMP6, KNNMB4 and DYM were candidates for the GP202 gastric cancer cell line and the genes TXNL4B, FOXK1, PTPRJ, and SNN were candidates for the IPA220 gastric cancer cell line." (PMID 19563644, 2009).
glioblastoma (6 papers, 2012 to 2023). The most malignant astrocytic tumor (WHO grade IV). "For instance, depletion of PLA2G4A caused significant decrease in cellular proliferation in glioblastoma, lung cancer and colon cancer cells." (PMID 33536020, 2021). "Our previous study has reported that PTRF involves in regulating lipid metabolism reprogramming via stabilizing the PLA2G4A in glioblastoma cells." (PMID 35547748, 2022). "Silencing the expression of PLA2G4A considerably suppresses the survival and proliferation of lung cancer cells, glioblastoma cells, and colon cancer cells." (PMID 35241089, 2022). "PLA2G4A depletion significantly repressed cellular proliferation in glioblastoma, lung cancer and colon cancer." (PMID 33536020, 2021). "In a subcutaneous xenograft model of glioblastoma, expression of PLA2G4A by the host mice was required for tumor growth." (PMID 23046790, 2012). "Specifically, cytosolic phospholipase A2 (cPLA2)α/PLA2G4A and various sPLA2, including PLA2G5, show increased expression in glioblastoma." (PMID 37046844, 2023).
Alzheimer disease (5 papers, 2014 to 2026). A progressive, neurodegenerative disease characterized by loss of function and death of nerve cells in several areas of the brain leading to loss of cognitive function such as memory and language. "Further, four genes are correlated with neuropsychiatric traits such as behavioral disorders, panic disorders, or Alzheimer's disease (MYRFL, TNEN132, RNFT2, and PLA2G4A)." (PMID 37337823, 2023). "mRNA and protein levels of cPLA2 IVA (PLA2G4A), sPLA2 IIA (PLA2G2A), COX-1 and -2 (PTGS1, PTGS2), mPGES1 (PTGES1), and LOX-12 and -15 (ALOX12B, ALOX15B), are increased in Alzheimer's disease in the frontal cortex, hippocampus, and cerebellum." (PMID 24963629, 2014). "Genes whose mRNA levels decline with age have significantly greater promoter DNA damage, so some mechanism may prevent normal downregulation of PLA2G4A and PTGS2 in Alzheimer's disease." (PMID 24963629, 2014).
lung carcinoma (5 papers, 2015 to 2022). "We extensively characterize drug hits in silico, demonstrating that they slow growth significantly in nine lung cancer cell lines from the NCI-60 collection, and identify CALM1 and PLA2G4A as promising drug targets for lung cancer." (PMID 25786242, 2015). "There are 4 drugs targeting PLA2G4A included in the CMap collection, and all 4 significantly reverse lung cancer gene changes in our analyses: flunisolide, fluocinonide, fluorometholone, and medrysone." (PMID 25786242, 2015).
Obesity (5 papers, 2016 to 2025). Accumulation of substantial excess body fat. "Our findings in the non-human primate support emerging data from human studies that polygenic variants in lipid metabolism (APOB) and central enzymes for mediating eicosanoid-driven inflammation (PLA2G4A) modulate obesity-resistant traits in response to dietary challenge or supplementation." (PMID 27811965, 2016). "A higher expression of PLA2G2D, PLA2G4A and PLA2G7 were found in scWAT of individuals living with healthy obesity." (PMID 38024342, 2023). "Accordingly, PLA2G2A and PLA2G4A genes were up-regulated by omega-3 polyunsaturated fatty acids supplementation, whereas SLC27A2, CNR1, DAGLA, MGLL, FAAH, SLC27A1, and SLC27A2 genes were found to be down-regulated in people living with healthy obesity." (PMID 38024342, 2023). "In contrast, neither APOB.2 nor PLA2G4A demonstrated a significant effect on weight change (one phenotypic characteristic which renders of fails to render obesity)." (PMID 27811965, 2016).
acute myeloid leukemia (4 papers, 2021 to 2025). Acute myeloid leukemia (AML) is a group of neoplasms arising from precursor cells committed to the myeloid cell-line differentiation. "A separate analysis of the hematological cancer cell lines showed multiple myeloma had the highest PLA2G4A copy number and that the highest PLA2G4A gene expression was in acute myeloid leukemia (AML) lines." (PMID 34946532, 2021). "Analysis of RNA-seq and copy number data using the CCLE showed that the PLA2G4A gene was most highly expressed in melanoma and certain leukemia and lymphoma cell lines, including acute myeloid leukemia (AML) and multiple myeloma (MM)." (PMID 34946532, 2021). "Analysis of 10,131 hematological cancer patient samples showed the highest gene expression of PLA2G4A was in lymphoma, acute myeloid leukemia (AML), and multiple myeloma (MM)." (PMID 34946532, 2021). "We also found PLA2G4A to be highly expressed in certain hematological cancers, including acute myeloid leukemia (AML), which is consistent with the previous reports of overexpression of PLA2G4A in leukemias, and also in multiple myeloma and lymphoma, which has not previously been reported." (PMID 34946532, 2021).
asthma (4 papers, 2017 to 2023). "Differences in the lengths of microsatellite sequences in the promoter region of PLA2G4A were reported between patients with severe asthma and healthy controls, with a direct impact on mRNA and protein expression, suggesting a role in asthma pathogenesis." (PMID 27504716, 2017). "Further, rs932476 in PLA2G4A and rs931127 in RELA were also marginally associated with asthma (p = 0.0036 and p = 0.035, respectively)." (PMID 27504716, 2017). "This study identified interactions between genetic variants near or within five genes, PLA2G4A, PLA2R1, RELA, PRKD1 and PRKCA, and occupational exposures to LMW agents or irritants for current adult-onset asthma." (PMID 27504716, 2017). "As shown in, 6 essential oil compositions could act on PLA2G4A and ALOX5 and be associated with asthma." (PMID 35702766, 2023). "Overall, all these data suggest that any or all of these genes—PLA2G4A, PLA2R1, RELA, PRKD1, and PRKCA—may play a role in the risk of asthma in adults in association with exposure to LMW agents or irritants." (PMID 27504716, 2017).
autism (4 papers, 2017 to 2025). Persistent deficits in social interaction and communication and interaction as well as a markedly restricted repertoire of activity and interest as well as repetitive patterns of behavior.
cerebral infarction (4 papers, 2018 to 2022). An ischemic condition of the brain, producing a persistent focal neurological deficit in the area of distribution of the cerebral arteries. "For example, miR-145-5p suppresses the activation of activated microglia cells in cerebral infarction by targeting the 3′UTR of PLA2G4A." (PMID 36203804, 2022).
colitis (4 papers, 2012 to 2023). Inflammation of the colon. "The phosphorylated forms of PLA2G4A (p-cPLA2α) was found up-regulated in the colon tissues of DSS-induced colitis mice and suppressed by berberine treatment." (PMID 33658925, 2020). "We then demonstrated berberine inhibits the phosphorylation of cytosolic phospholipase A2a (PLA2G4A) in the colon tissue of experimental colitis mice and inflamed macrophage RAW 264.7 cells." (PMID 33658925, 2020). "In other experiments, berberine has been shown to directly bind to PLA2G4A and inhibit the MAPK/JNK signaling pathway to suppress PLA2G4A activity in murine colitis." (PMID 37701897, 2023). "The cytosolic phospholipase A2a (PLA2G4A), an enzyme for hydrolyzing PC to LPC, was found to be up-regulated in the colon tissue of experimental colitis mice and inflamed macrophage RAW 264.7 cells." (PMID 33658925, 2020).
COVID-19 (4 papers, 2020 to 2023). A disease caused by infection with severe acute respiratory syndrome coronavirus 2. "Current clinical studies have shown that the expression levels of inflammatory factors (IL-2, IL-7, IFN-γ, and TNF-α) positively correlate with the severity of COVID-19, suggesting that PLA2G4A may be a key target in the development of COVID-19." (PMID 36210820, 2022). "Meanwhile, QFPD may play a role in COVID-19 treatment by targeting mTOR and PLA2G4A." (PMID 36210820, 2022). "In fact, we observed that GC therapy elevated cPLA2 enzyme-corresponding genes (PLA2G4A and PLA2G5) in COVID-19 patient blood cells." (PMID 36851787, 2023). "We next sought to determine which formulation was superior in treating mild-to-moderate COVID-19 with symptoms of depression or inflammation via targeting specific targets (GRM1, GRM5, mTOR and PLA2G4A)." (PMID 36210820, 2022). "The gene expression of PLA2 isoforms, PLA2G4A and PLA2G5, were upregulated, while PLA2G6 and PLA2G7 were downregulated in COVID-19 patients using GCs, compared to non-treated COVID-19 patients and controls." (PMID 36851787, 2023).
prostate carcinoma (4 papers, 2021 to 2025). A carcinoma that arises from epithelial cells of the prostate gland. "Among the UPR branches, ATF6α has been shown to promote prostate cancer progression by upregulating PLA2G4A (cytosolic phospholipase A2)-mediated arachidonic acid metabolism, leading to elevated prostaglandin production and resistance to ferroptotic cell death in tumor cells." (PMID 41228282, 2025). "Furthermore, it could regulate arachidonic acid metabolism via the ATF6α–PLA2G4A signaling pathway to promote prostate cancer progression, or promote the malignancy through a reciprocal negative feedback mechanism with PTEN." (PMID 39080273, 2024). "In addition, FASN inactivation with siRNA in LNCaP cells reduces pseudopodia and invadopodia formation, cell adhesion, migration and invasion, and FASN inhibition negatively regulates PLA2G4A and HSD17B12 in several prostate cancer cell lines." (PMID 33166087, 2021). "Finally, FASN inhibition negatively regulates cytosolic phospholipase A2 (PLA2G4A) and estradiol 17‐beta‐dehydrogenase 12 (HSD17B12) in several prostate cancer cell lines." (PMID 33166087, 2021).